PLEKHG2 (pleckstrin homology and RhoGEF domain containing G2)
Description:
May be a transforming oncogene with exchange activity for CDC42 (By similarity). May be a guanine-nucleotide exchange factor (GEF) for RAC1 and CDC42. Activated by the binding to subunits beta and gamma of the heterotrimeric guanine nucleotide-binding protein (G protein). Involved in the regulation of actin polymerization.
Synonyms: CLG; FLJ00018; ARHGEF42; CTB-60E11.4; LDAMD
Tractability: PROTAC: ubiquitination databases record sites on it.
Gene: Protein-coding gene on chromosome 19 (39,412,669 to 39,428,415, forward strand). Ensembl gene ENSG00000090924.
Subcellular location (Human Protein Atlas): Nucleoplasm; Cytosol
Pathways (Reactome):
Signal Transduction: CDC42 GTPase cycle; G alpha (12/13) signalling events; NRAGE signals death through JNK; RAC1 GTPase cycle
Gene Ontology:
Molecular function: protein binding; guanyl-nucleotide exchange factor activity; small GTPase binding
Biological process: regulation of actin filament polymerization
Cellular component: cytosol
Genetic constraint (gnomAD): Loss-of-function variants: 73 observed, 102.78 expected, observed/expected ratio (o/e) 0.71, 90% interval 0.59 to 0.86. The upper end of that interval is the gene's LOEUF score, 0.86, which puts it in group 3 of 6, group 1 being the genes least tolerant of losing a copy. Missense variants: 1,730 observed, 1,814.4 expected, observed/expected ratio (o/e) 0.95, 90% interval 0.92 to 0.99. Synonymous variants: 728 observed, 729.48 expected, observed/expected ratio (o/e) 1, 90% interval 0.94 to 1.06.
Homologues: Orthologues: chimpanzee PLEKHG2 (99% identical), macaque PLEKHG2 (95% identical), pig PLEKHG2 (79% identical), dog PLEKHG2 (78% identical), guinea pig PLEKHG2 (76% identical), rat Plekhg2 (71% identical), mouse Plekhg2 (71% identical). Paralogues in human: PLEKHG1 (23% identical), MCF2L (11% identical), TRIO (11% identical), KALRN (10% identical), TIAM2 (9% identical), PLEKHG4 (8% identical), VAV2 (8% identical), TIAM1 (8% identical), MCF2L2 (8% identical), MCF2 (8% identical), ARHGEF7 (8% identical), SPATA13 (8% identical), and 10 more.
Diseases named in the same sentence as PLEKHG2 in open-access papers:
PLEKHG2 is named in the same sentence as 19 diseases in open-access papers, as found by Europe PMC text mining. Sharing a sentence is not in itself a finding about the gene and the disease. The quoted sentences say what the papers report.
Ataxia (2 papers, 2022 to 2023). Ataxia refers to impaired coordination of voluntary muscle movement. "A subset of FS symptoms, such as dystonia, myoclonus, and ataxia, may be attributed to the downregulation of PLEKHG2, DST, ARX, AAAS, KCTD17, PRDM8, and CRTC1 in FS brains as these genes are downregulated in Q84Pfs-Het brains and play a role in these movement and muscle coordination 43–49." (PMID 37398410, 2023).
Dystonia (2 papers, 2020 to 2023). An abnormally increased muscular tone that causes fixed abnormal postures. "Variants in LGI4 cause arthrogryposis multiplex congenital; variants in PLEKHG2 cause mental retardation, dystonia and microcephaly; and those in PLEC1 have been shown to be involved in a renal disease (nephrotic syndrome)." (PMID 32340215, 2020).
microcephaly (2 papers, 2020 to 2022). A congenital or acquired developmental disorder in which the circumference of the head is smaller than normal for the person's age and sex. "The p.Arg204Trp variation in PLEKHG2 is reported to cause “postnatal” microcephaly; head circumference of the patients were normal at birth and fell in percentiles to approximately −3 S.D. at 4–6 months of age." (PMID 35203342, 2022). "Considering that Plekhg2-knockdown had little effect on neuronal precursor proliferation, the postnatal microcephaly associated with the PLEKHG2 variation is supposed to be caused by defects in neurite growth after birth." (PMID 35203342, 2022). "Homozygosity of the p.Arg204Trp variation in the Pleckstrin homology and RhoGEF domain containing G2 (PLEKHG2) gene, which encodes a Rho family-specific guanine nucleotide-exchange factor, is responsible for microcephaly with intellectual disability." (PMID 35203342, 2022). "The p.Arg204Trp variant in PLEKHG2 is responsible for postnatal microcephaly and ID." (PMID 35203342, 2022). "Additionally, the p.Arg204Trp variation in PLEKHG2 is known to cause neurodevelopmental disorders with microcephaly and ID." (PMID 35203342, 2022). "The obtained results indicate that PLEKHG2 has essential roles in brain development, and disruption of its function may cause defects in neuronal development, which lead to ID and microcephaly." (PMID 35203342, 2022). "Considering the relationship of microcephaly with the PLEKHG2 variation, impaired RAC1-signaling might be partially related to the clinical features of the patients." (PMID 35203342, 2022). "Recently, whole-exome sequence analysis has identified a homozygous missense variation resulting in, c.610C > T/p.Arg204Trp, in the PLEKHG2 protein of five patients with profound intellectual disability (ID), dystonia, postnatal microcephaly, and a distinctly abnormal neuroimaging pattern." (PMID 35203342, 2022).
pancreatic cancer (2 papers, 2021 to 2025). "Upregulation of PLEKHG2 has been observed in lung and pancreatic cancer where it correlated with poor survival." (PMID 40522948, 2025). "In pancreatic cancer, PLEKHG2 has a purported role as a 19q13 amplicon driver." (PMID 34788622, 2021).
breast carcinoma (1 paper, 2021). "Higher PLEKHG2 mRNA expression was consistently associated with worse patient outcome across four large transcriptomic datasets, representing a diverse range of cancer types and mostly primary tumors such as TCGA pan-cancer, lung adenocarcinoma, pediatric brain tumors, and breast cancer." (PMID 34788622, 2021).
developmental delay (1 paper, 2022). "MD-181 (homozygous PLEKHG2 p.T53I) showed very early-onset hypotonia, and developmental delay rapidly evolved into spastic-dystonic tetraparesis from 6 months old, when subtle symmetrical T2 hyperintensities on thalami and deep white matter were detected." (PMID 36233161, 2022).
Immunodeficiency (1 paper, 2023). Failure of the immune system to protect the body adequately from infection, due to the absence or insufficiency of some component process or substance. "Restricted by laboratory conditions, we have only explored the role and mechanism of PLEKHG2 in NSCLC in immunodeficiency models." (PMID 38021149, 2023).
cancer (3 papers, 2021 to 2023). A tumor composed of atypical neoplastic, often pleomorphic cells that invade other tissues. "Bioinformatics analysis performed on the NSCLC dataset from GEO and TCGA in These paradoxical results suggest that PLEKHG2 may have different roles in various cancers." (PMID 38021149, 2023). "These paradoxical results suggested that PLEKHG2 may have different roles in various cancer." (PMID 38021149, 2023). "EVs exclusively contained PLEKHG2 (nucleotide-binding protein), GPR68 (a proton sensing G protein-coupled receptor 68), POU4F2, ADAMTS9, and Let-7 microRNA precursor, which are involved in cell development, signal transduction, and cancer metastasis." (PMID 35663013, 2022).
tumor (2 papers, 2008 to 2023). "In summary, PLEKHG2 showed broadly upregulated expression in tumor tissues and was correlated with poor prognosis in NSCLC patients." (PMID 38021149, 2023). "Among the four tumor cell lines, mRNA expression levels of PLEKHG2 were 5.16- and 20.04-fold higher in A549 and H1299 cells, respectively, compared with 16HBE cells (P <0.05)." (PMID 38021149, 2023). "Meanwhile, PLEKHG2 protein levels were also found to be increased in all four tumor cell lines compared with 16HBE cells." (PMID 38021149, 2023). "PLEKHG2 was barely detected in paraneoplastic tissues, while intracellular PLEKHG2 was clearly seen in the nucleoplasm and cytosol of tumor tissues." (PMID 38021149, 2023). "We demonstrated that GULT1 and HK2 protein levels were positively correlated with PLEKHG2 expression in tumor tissues both in vivo and in vitro." (PMID 38021149, 2023). "Thus, we further validated the effects of PLEKHG2 knockdown on NSCLC tumor growth in the H1299 xenograft tumor model." (PMID 38021149, 2023). "Furthermore, we detected PLEKHG2 expression in NSCLC cell lines and tumor tissues from patients and confirmed that PLEKHG2 expression was upregulated in NSCLC." (PMID 38021149, 2023). "The list of genes with reduced expression in DA, as compared with increased expression in DA.F344(Cia5d) congenics, included seven genes that are involved in tumor suppression-like activity and cell cycle check-points, such as Aph1a, Brwd3, Gadd45b, Gmfg, Lox, and Plekhg2." (PMID 18706093, 2008). "Finally, we found that PLEKHG2 knockdown inhibited the tumor growth in the H1299 CDX model." (PMID 38021149, 2023). "Bioinformatics analysis performed on NSCLC datasets from GEO and TCGA indicated that PLEKHG2 expression was increased in tumor tissues compared with normal lung tissues and that high PLEKHG2 expression was associated with poor prognosis." (PMID 38021149, 2023).
neurodevelopmental disorder (1 paper, 2022). A behavioral and cognitive disorder with onset during the developmental period that involves impaired or aberrant development of intellectual, motor, or social functions. "Moreover, impairment of PLEKHG2 function is most likely to cause defects in neuronal functions that lead to neurodevelopmental disorders." (PMID 35203342, 2022).
PLEKHG2 also shares sentences with these, for which no sentence is quoted: B-cell lymphoma (1 paper); Encephalopathy (1); Intellectual disability (1); leukemia (1); lung adenocarcinoma (1); metastatic tumors (1); nephrotic syndrome (1); neurological disorder (1); renal disease (1).